REG1B (regenerating family member 1 beta)
Description:
Might act as an inhibitor of spontaneous calcium carbonate precipitation. May be associated with neuronal sprouting in brain, and with brain and pancreas regeneration.
Synonyms: PSPS2; REGL; REGH; REGI-BETA
Tractability: Antibody: UniProt places it where antibodies can reach, with medium confidence; UniProt predicts a signal peptide or a membrane-spanning region; its Gene Ontology location is reachable by antibodies, with medium confidence.
Gene: Protein-coding gene on chromosome 2 (79,085,023 to 79,088,019, reverse strand). Ensembl gene ENSG00000172023.
Subcellular location: Secreted
Gene Ontology:
Molecular function: protein binding; growth factor activity; hormone activity
Biological process: antimicrobial humoral immune response mediated by antimicrobial peptide; positive regulation of cell population proliferation; response to peptide hormone; signal transduction
Cellular component: extracellular exosome; extracellular region
Genetic constraint (gnomAD): Loss-of-function variants: 18 observed, 18.8 expected, observed/expected ratio (o/e) 0.96, 90% interval 0.66 to 1.42. The upper end of that interval is the gene's LOEUF score, 1.42, which puts it in group 5 of 6, group 1 being the genes least tolerant of losing a copy. Missense variants: 213 observed, 178.85 expected, observed/expected ratio (o/e) 1.19, 90% interval 1.06 to 1.33. Synonymous variants: 73 observed, 69.15 expected, observed/expected ratio (o/e) 1.06, 90% interval 0.87 to 1.28.
Homologues: Orthologues: chimpanzee REG1B (99% identical), macaque REG1B (96% identical), rat Reg3g (46% identical), mouse Reg3a (45% identical), mouse Reg3d (44% identical), rat Reg3b (44% identical), mouse Reg3b (43% identical), mouse Reg3g (43% identical), rat Reg3a (42% identical), zebrafish zgc:172053 (28% identical), zebrafish si:ch211-125e6.5 (28% identical), zebrafish si:dkey-241l7.4 (27% identical), and 16 more. Paralogues in human: REG1A (87% identical), REG3G (49% identical), REG3A (49% identical), REG4 (31% identical), CLEC19A (30% identical).
Diseases named in the same sentence as REG1B in open-access papers:
REG1B is named in the same sentence as 24 diseases in open-access papers, as found by Europe PMC text mining. Sharing a sentence is not in itself a finding about the gene and the disease. The quoted sentences say what the papers report.
inflammatory bowel disease (5 papers, 2013 to 2023). A spectrum of small and large bowel inflammatory diseases of unknown etiology. "REG1B protein is highly expressed in several human pathologies, such as inflammatory bowel disease, many of which are associated with epithelial inflammation, indicating that the gastric mucosa of Muc1−/− mice is more inflamed than WT mice within 8 h of infection." (PMID 32793510, 2020). "DGE of the lower villus zone revealed that NEC epithelial cells exhibited substantial increase in the antimicrobial genes LCN2, REG1A, REG1B, and DMBT1, genes previously shown to be elevated in inflamed epithelium associated with inflammatory bowel disease (IBD)." (PMID 37205711, 2023). "REG1A and REG1B are upregulated in human colonic or gastric mucosa with inflammatory bowel disease (IBD) and ulcerative colitis (UC)." (PMID 31696115, 2019). "SYCN has not previously been studied in other cancers; however REG family gene expression, although not REG1B specifically, has been shown previously to be elevated in colon cancer and inflammatory bowel disease." (PMID 24007603, 2013).
pancreatic cancer (5 papers, 2013 to 2025). "Another study published in the same journal in 2017 found that REG1B levels were higher in the urine of pancreatic cancer patients compared to healthy controls and patients with chronic pancreatitis." (PMID 37322046, 2023). "REG1A, REG1B, and REG3A were reported to be increased in cancer ductal fluid, and REG1A was linked to pancreatic cancer." (PMID 37107224, 2023). "A study published in the journal Pancreas in 2014 found that REG1B was significantly elevated in the serum of pancreatic cancer patients compared to healthy controls and patients with pancreatitis." (PMID 37322046, 2023). "In this study, we found significant elevations of Reg1A and Reg1B in the sera of pancreatic cancer patients in comparison to normal healthy subjects." (PMID 27788482, 2016). "Additional serum biomarkers, particularly SYCN and REG1B, when combined with CA19.9, show promise as improved diagnostic indicators of pancreatic cancer, which therefore warrants further validation." (PMID 24007603, 2013). "In the present study, REG1B was significantly elevated in pancreatic cancer serum/plasma compared to healthy and benign disease controls, and it was a component of all three panels found to significantly improve the AUC of CA19.9 in our training and validation analyses." (PMID 24007603, 2013). "REG1A, a protein that is highly similar to REG1B has been implicated in pancreatitis, and other REG family members such as REGIV and hepatocarcinoma-intestine-pancreas/pancreatitis associated protein I (HIP/PAPI) have shown potential diagnostic utility for pancreatic cancer." (PMID 24007603, 2013). "In their study, Patel & Mukherjee66 developed a neural network model using four urine biomarkers (REG1A, REG1B, LYVE1, and TFF1) to predict locally progressed pancreatic cancer." (PMID 40269234, 2025). "The illustration also indicates that age, sex, plasma CA19-9, creatinine, LYVE1, REG1B, TFF1, and REG1A have a positive correlation in the diagnosis of pancreatic cancer meaning that they are statistically significant predictors of pancreatic cancer diagnosis." (PMID 40269234, 2025). "In the current study, four pancreatic cancer biomarker candidates (SYCN, REG1B, AGR2 and LOXL2) delineated through our previous integrated proteomics analysis of cell line conditioned media and pancreatic juice, were validated in two sample sets of serum/plasma containing a total of 432 samples." (PMID 24007603, 2013).
colon cancer (3 papers, 2013 to 2019). "Further studies are still needed to explore the biological functions and underlying molecular mechanisms of REG1B, TGM6, NTF4, PNMA5, and HOXC13 in colon cancer." (PMID 30884206, 2019). "The prognostic signature based on REG1B, TGM6, NTF4, PNMA5, and HOXC13 could divide colon cancer patients into high–risk and low–risk groups, with an AUC of the ROC of 0.771." (PMID 30884206, 2019). "We also propose that developing inhibitors that prevent the interaction between HLTF and the REG1B promoter could be useful to reduce the expression of REG-1β after colon regeneration, and thus reduce the risk of colon cancer." (PMID 29807746, 2018). "We then constructed a prognostic signature based on the expression of REG1B, TGM6, NTF4, PNMA5, and HOXC13 which could provide significant prognostic value for colon cancer." (PMID 30884206, 2019). "Using these data, we constructed a prognostic signature based on the expression of REG1B, TGM6, NTF4, PNMA5, and HOXC13 which could provide great significant prognostic value for colon cancer." (PMID 30884206, 2019).
enteropathy (3 papers, 2021 to 2025). "It is worth noting that the targeted drug alanyl glutamine targeting REG1B is entering inflammation, phase III trial of nutrition and enteropathy." (PMID 41261599, 2025). "Although our drug target prediction did not predict drugs targeting REG1B, it is worth noting that REG1B is currently undergoing clinical trials for inflammation, nutrition, and enteropathy." (PMID 41261599, 2025).
ulcerative colitis (3 papers, 2021 to 2023). An inflammatory bowel disease involving the mucosal surface of the large intestine and rectum. "Expression of REG1B and Calprotectin are elevated in tissue samples from patients with benign diseases, such as acute amoebic colitis, Crohn’s disease and ulcerative colitis." (PMID 34957214, 2021).
chronic pancreatitis (2 papers, 2016 to 2022). A chronic inflammatory process causing damage and fibrosis of the pancreatic parenchyma. "We also observed statistically insignificant elevations of Reg1A and Reg1B in the sera of chronic pancreatitis compared to normal controls." (PMID 27788482, 2016). "There were only slight elevations of Reg1A and Reg1B levles in the sera of chronic pancreatitis compared to the normal controls which were not statistically significnant (mid column)." (PMID 27788482, 2016).
Blastocystis infection (1 paper, 2021). "Similarly, a statistically significant negative association was observed between Blastocystis infection and fecal concentrations of REG1B (β = -0.66; 95% CI = -1.06, -0.26; p-value = 0.001) in adjusted model." (PMID 34407080, 2021).
colitis (1 paper, 2020). Inflammation of the colon. "We observed a universal upregulation of REG1A/REG1B across subtypes of UC, including both active extensive colitis and inactive extensive colitis." (PMID 32731480, 2020).
diabetes mellitus (1 paper, 2023). A metabolic disorder characterized by abnormally high blood sugar levels due to diminished production of insulin or insulin resistance/desensitization. "In the unhealthy population they co-occur with REG1A, REG1B, CPB1, and REG3A, all involved in diabetes mellitus and malignant neoplasms." (PMID 37021928, 2023).
Insulin resistance (1 paper, 2022). Increased resistance towards insulin, that is, diminished effectiveness of insulin in reducing blood glucose levels. "Regardless of insulin resistance, the two groups of women with morbid obesity showed upregulation of LYPD8 and downregulation of a greater number of genes, such as REG1B, GKN2, LPL, PNLIPRP2, FKBP5, and CD86, that are related to responses to bacterial stimuli and antimicrobial activity." (PMID 35625760, 2022).
intrahepatic cholangiocarcinoma (1 paper, 2016). A carcinoma that arises from the intrahepatic bile duct epithelium in any site of the intrahepatic biliary tree. "Furthermore, tissue expressions of Reg1A, Reg1B, and Reg4 could differentiate metastatic PDAC in the liver from intrahepatic cholangiocarcinoma with 92% sensitivity and 95% specificity." (PMID 27788482, 2016).
Obesity (1 paper, 2024). Accumulation of substantial excess body fat. "This analysis showed that some proteins, such as COL1A1, COL6A3, FABP4, LEP, LGALS1, and THBS4, are obesity-specific, and GDF15, LPL, MCFD2, REG1A, REG1B, and TCN2 are T2D-specific." (PMID 38732002, 2024).
pancreatic ductal adenocarcinoma (1 paper, 2021). An infiltrating adenocarcinoma that arises from the epithelial cells of the pancreas. "Regenerating proteins, including REG1A and REG1B, promoted acinar-to-ductal metaplasia and acted as novel diagnostic and prognostic markers in pancreatic ductal adenocarcinoma." (PMID 34055623, 2021).
cancer (9 papers, 2013 to 2023). A tumor composed of atypical neoplastic, often pleomorphic cells that invade other tissues. "We analyzed the first 10 mRNAs screened and found that in addition to the REG1B reported to be involved in the biological function of cancer cells, the remaining nine have been associated with CRC." (PMID 30039525, 2018). "More interestingly, most of the signature genes in Cluster 1 were same to those of metastatic cancer cells, including REG1B, MEG3 and CPA1, this was possibly because of the major cell contribution of this cluster from metastatic PDAC." (PMID 34055623, 2021). "While REG1A expression increases with progression from PanINs to cancer, REG1B is already highly expressed in the earliest PanINs, which is in agreement with our data showing that REG1B is an earlier marker." (PMID 33301466, 2020). "The intensity of staining for Reg1A and Reg1B in these cancer cells was much stronger than that of Reg4, despite the fact that Reg4 had previously been reported as a biomarker of PDAC." (PMID 27788482, 2016). "Expression of human REG1B, an orthologue of mouse REG2, is altered under conditions of inflammatory diseases, cancer, and childhood stunting." (PMID 37107224, 2023). "PDAC cancer tissues showed 22-fold and 6-fold increases of Reg1A and Reg1B mRNA levels than the adjacent non-neoplastic acinar tissues (P=0.025 and 0.016)." (PMID 27788482, 2016). "Immunohistochemically, the infiltrative PDAC cancer glands stained strongly positive for Reg1A and Reg1B, but negative for Reg3A/G." (PMID 27788482, 2016). "SYCN, REG1B and AGR2 were also significantly elevated in PDAC compared to benign controls (p ≤ 0.01), and AGR2 was significantly elevated in PDAC compared to other cancers (p < 0.01)." (PMID 24007603, 2013).
infection (3 papers, 2020 to 2025). The state of being infected such as from the introduction of a foreign agent such as serum, vaccine, antigenic substance or organism. "The study results also corroborate that infection with H. pylori had significant positive association with fecal Alpha-1 antitrypsin concentrations and an inverse relationship with Reg1B concentrations measured in stool samples of the children." (PMID 32324737, 2020). "An inverse association was observed between the infection and fecal Reg1B concentrations of these children." (PMID 32324737, 2020). "On the other hand, fecal Reg1B concentration measured at the end of the study was lower in children who acquired infection during the study and who remained infected in both the time points." (PMID 32324737, 2020). "Children who acquired infection during study (p-value = 0.03) and who remained infected in the both the time points (p-value = 0.006) had significantly lower concentrations of fecal Reg1B compared to the reference group." (PMID 32324737, 2020). "Infection with H. pylori had significant positive association with fecal AAT concentrations (Coefficient = 0.26; 95% CI = 0.02, 0.49; p-value = 0.03) and inverse relationship with Reg1B concentrations measured in the stool samples (Coefficient = -0.32; 95% CI = -0.59, -0.05; p-value = 0.02)." (PMID 32324737, 2020).
tumor (3 papers, 2014 to 2020). "Both REG1A and REG1B upregulation was demonstrated in precursor lesions, which resulted in an accelerated cell proliferation and tumour growth." (PMID 33301466, 2020). "High grade PDAC with low levels of Reg1A and Reg1B showed a statistically significant lower survival rate after tumor resection, when compared to those with low grade PDAC and high levels of Reg1A and Reg1B (P<0.0001, P<0.001 and P<0.001)." (PMID 27788482, 2016). "Mohammad showed that gene losses of AMY2A, TGFA, and REG1B in uterine leiomyosarcoma may be responsible for secondary changes that affect the progression and proliferation of the tumor." (PMID 24743780, 2014).
REG1B also shares sentences with these, for which no sentence is quoted: Crohn disease (1 paper); infectious colitis (1); inflammation (1); malaria (1); metabolic syndrome (1); morbid obesity (1); pancreatitis (1); ulcers (1).